IL10 (interleukin 10)
Diseases named in the same sentence as IL10 in open-access papers (continued):
Sharing a sentence is not in itself a finding about the gene and the disease.
myeloma (continued). "An increasing in the secretion of IL-10 and TGF-β by MDSC is induced by the S100A9-CD33 interaction with myeloid cells, which promotes the formation of multiple myeloma." (PMID 34689842, 2021). "Myeloma cells produce proteins such as TGF- ß, PD-L1, LAG3, TIM3, and IL10 that contribute to the immunosuppressive phenotype and T cell anergy." (PMID 33634031, 2020). "Increased levels of key cytokines have also been shown to progressively increase from controls to smouldering myeloma to multiple myeloma including CXCL8 (IL-8), IL-10, TNFα, IL6 and IFNγ." (PMID 28389623, 2017). "Out of them, one factor was significantly regulated in myeloma-stroma cell coculture treated with bortezomib +/− CCL27, i.e. IL-10." (PMID 27732933, 2016). "For example, IL-1β, IL-6, IL-10, IFN-α, IGF-1 and TGF-γ promote proliferation of multiple myeloma cells, whereas IFN-β1 and APO-1/FAS inhibit the growth of multiple myeloma cells." (PMID 22792345, 2012). "Immunological inhibitory cytokines, such as TGF-β, IL-10, IL-6 and VEGF, which are produced from myeloma cells, can modulate antitumor host immune response, including the abrogation of DC function, by constitutive activation of STAT3." (PMID 22481968, 2012). "IL-10 drives the proliferation and differentiation of activated B cells and has recently proved to promote the proliferation of primary myeloma cells, although it does not induce plasma cell differentiation or immunoglobulin secretion." (PMID 37250588, 2023). "MDSC production of S100A9, a calcium-binding protein that promotes the release of TNF-α, IL-6, and IL-10 in autocrine pathway through TLR4 interaction, attracts myeloma cells in the TME and supports myeloma cell growth via the activation of the canonical NFκB pathway." (PMID 36726975, 2022). "Furthermore, some recent data indicated that IL-32 induced anti-inflammatory cytokines, such as IL-10 and the immunosuppressive molecules such as IDO in macrophages through STAT3 and nuclear factor κB pathway, and promoted multiple myeloma development." (PMID 34414188, 2021). "Within myeloma niche, after interaction with BM-derived mesenchymal stromal cells, TAMs acquire a secretory profile characterized by a great production of IL-6 and IL-10 and poor production of IL-12 and TNF-α, providing a suitable milieu for myeloma plasma cell growth." (PMID 33194767, 2020). "The observation that myeloma-reactive PD-1+ CD4+ and CD8+ T cells secrete both IFN-γ and IL-10 suggests these cells may be at the crossroads of an immune switch from effector to tolerogenic." (PMID 28642819, 2017). "Enhanced IL-10 levels foster phosphorylation of the survival molecule STAT-3 as well as modulation of proteasomal activity and shedding of immunoglobulins, contributing to myeloma survival under treatment." (PMID 27732933, 2016). "For this analysis we used A20, a mature B cell line known to secrete basal IL-10, BCL-1-3B3 cell line, a leukemic cell line that can be differentiated in vitro to plasma cells, and P3X63Ag8, a mouse plasmacytoma/myeloma cell line that expresses high levels of endogenous IRF4." (PMID 24391506, 2014). "In this respect, both TGF-β and IL-10 are known to modulate IDO1 and may be expressed by the myeloma cells during progressive disease." (PMID 23232072, 2012). "MSCs in the myeloma BMME suppress T cell activation and proliferation, impair DC maturation, and induce Tregs via the secretion of several cytokines and interleukins such as IL-6, TGF-β, IL-10, and upregulation of surface molecules such as VCAM-1, ICAM-1, or CD40." (PMID 35886976, 2022). "MSCs from myeloma patients (MM-MSCs) interrelate with MM cells and change the expression of certain angiogenic and growth factors (such as CD40/40L, VCAM-1, ICAM-1, LFA-3 and HO-1) and several cytokines (IL-6, IL-10 TGFb1, macrophage inflammatory protein-1b (MIP-1b) and IL-7)." (PMID 33923357, 2021).
myeloma (continued). "In addition, our results showed that the ability of Treg cell subsets to secrete IL-10 in untreated myeloma patients was not different from that of healthy controls." (PMID 30479566, 2018). "DCs combined with lenalidomide and PD-1 blockade also heightened the anti-myeloma cell mediate immunity by inducing the Th1 polarization, as evidenced by the high-level production of IFN-γ, and by suppressing Th2 immune responses, as evidenced by the low-level production of IL-10 and TGF-β." (PMID 29967612, 2018). "However, in vivo, IL-10 levels are not detectable in the majority of patients with established myeloma disease and expression appears to be mostly restricted to patients suffering from plasma cell leukemia." (PMID 27732933, 2016).
liver disease (58 papers, 2006 to 2026). "Prior work in S. mansoni-liver disease in cDC1-deficient Batf3-/- mice observed a protective role of anti-inflammatory IL-10-expressing CD8 T cells." (PMID 41055564, 2025). "Higher serum levels of IL-10 were estimated to be associated with higher inflammatory liver disease severity." (PMID 38138294, 2023). "Advanced liver disease predisposes to bacterial translocation and endotoxaemia which can contribute to elevated circulating levels of IL-10 and down-regulation of MHC class II on antigen-presenting cells." (PMID 23446058, 2013). "In the present study in patients with ACLF, we observed elevated serum levels of five cytokines commonly associated with inflammatory liver disease (IL-6, IL-8, IL-10, TNF-α, and sTNF-αR1) at baseline." (PMID 17156425, 2006). "In addition to IL-10, IL-6 has been implicated in the development of liver diseases and subsequent portal hypertension." (PMID 39997697, 2025). "Interestingly, taxon shifts in infected mice were those typically associated with protective effects on liver disease and IL-10 gut conditions, suggesting a possible protective role of the shifted microbiome." (PMID 40504882, 2025). "Notably, MCP-1 and IL-10 were also found to be the centers of networks associated with liver disease severity." (PMID 36612207, 2022). "Furthermore, in HCV infection, specific IL10 polymorphisms are correlated with increased susceptibility to the development of chronic infection and increased severity of hepatic disease." (PMID 33125400, 2020). "A wide spectrum of liver diseases associates with alteration of monocyte recruitment, phenotype or function, which could be modulated by IL-10." (PMID 20714353, 2010). "An imbalance of cytokines, namely Interleukin-1β (IL-1β), IL-6, and IL-10, can lead to liver diseases, including fibrosis and acute inflammation." (PMID 40584441, 2025). "Immune dysregulation is widely reported in patients with advanced liver disease, and our gene expression data showed significant differences in IL-10 and PDCD1 gene expression between patients with AD and healthy volunteers." (PMID 40126412, 2025). "Two studies from 1996 and 2000 showed a higher expression of IL-10 in patients with milder forms of hepatitis C than those with severe liver disease and a correlation between the downregulation of IL-10 and CHC." (PMID 36674897, 2023). "We found a decrease in plasma biomarkers (PD1, PDL1, CXCL10, CXCL8, IL12p70, IL10, and TGFβ) and liver disease markers (stiffness measurement (LSM), hepatic venous pressure gradient (HVPG), and transaminases, among others)." (PMID 34497613, 2021). "In another cohort, the frequencies of IL-10–producing B cells and serum IL-10 concentrations correlated positively with flare-ups of liver disease in patients with chronic hepatitis B infection." (PMID 34293057, 2021). "The heatmap illustrates the ability of IL10 expression to group patients according to liver disease progression and the plasma concentrations of liver enzymes." (PMID 33125400, 2020). "On admission, the levels of CRP and the production of the cytokines IL-6, IL-10, and M-CSF were significantly elevated in patients with a liver disorder." (PMID 32903864, 2020). "The median level of C-reactive protein (CRP) was higher in the hepatic disorder group, with a significantly higher concentration of IL-6, IL-10, and M-CSF." (PMID 32903864, 2020). "Further, C-reactive protein levels were much higher in the hepatic disorder group, with significantly higher concentrations of IL-6, IL-10, and M-CSF." (PMID 32903864, 2020). "Conversely, IL-10 production has beneficial effects on insulin sensitivity and protects against liver disease." (PMID 26588700, 2015). "In contrast to CHB patients, IL-10 was related to the HBeAg status, virus replication, and liver disease progression." (PMID 24288603, 2013).
liver disease (continued). "CXE is proven to suppress NO, pro-inflammatory (IL-6, IL-1β, and LDH), and apoptosis genes (Casp-9, Casp-3, and JNK) in APAP-mediated liver cells while increasing the expression of an anti-inflammatory agent (IL-10), which can be a potent target for liver disease treatment." (PMID 40584441, 2025). "Notably, the dataset includes many known proteins (IL6, IL10, IFNG, CSF3, PDGFB, CD40, and AFP) and novel proteins associated with liver diseases." (PMID 37209815, 2023). "Interleukin-10 (IL-10) family cytokines play a pivotal role in the progression of liver diseases." (PMID 37762066, 2023). "In addition, IL-10 correlated with the status of HBeAg, liver disease progression, and virus replication." (PMID 35265633, 2021). "Inflammatory mediators including TNF-α, IL-1β, and IL-10 may influence the progression of liver disease." (PMID 33117360, 2020). "IL-10 protects against hepatic IR injury by suppressing NF-κB activation and subsequent expression of proinflammatory mediators, and it has been shown to be beneficial in the setting of liver disease and transplantation." (PMID 31952110, 2020). "Interestingly, long-term treatment with recombinant IL-10 decreases liver disease in chronic HCV patients, but also leads to increased HCV viral levels via alterations in the host’s immunological viral surveillance." (PMID 27997563, 2016). "It is probable that increased cellular accumulation and the elevated production of inflammatory mediators such as IFNγ and CXCL9 as well as others not evaluated by this study accounts for the extent of liver disease in observed IL-10 deficient livers." (PMID 22880122, 2012). "In HCV infection, the influence of IL-10 genotypes either on different clinical features of liver disease or in the response to antiviral therapy has been evaluated in several studies: data are highly controversial with some studies showing a positive association and others denying such a link." (PMID 21251301, 2011). "Given the role of chronic liver diseases such as HBV and HCV in the development of portal hypertension, these findings suggest that genetic variations in IL-10 and its receptor may play a role in modulating the progression of liver fibrosis, and by extension, portal hypertension." (PMID 39997697, 2025). "We analyzed the association between changes in plasma biomarkers and liver disease severity scores (LSM and HVPG) during the follow-up, but we only found a positive association (p-value <0.05) between plasma variations of PD1, IL10, CXCL10, CCL2, and CXCL8 and the change in LSM values." (PMID 34497613, 2021). "Our data show an improvement in these immune and liver disease biomarkers in plasma (immune exhaustion (PD1), chemokines (CXCL10, CCL2, and CXCL8), and cytokines (IL10)) after achieving SVR with DAA therapy in HIV/HCV-coinfected individuals." (PMID 34497613, 2021). "Many studies have suggested that various cytokines, such as IL-2, IL-6, IL-8, IL-10, and IL-12 were involved in the progression of HBV-related liver disease and HCC." (PMID 31200663, 2019). "The diminution in IL-10 induction seen in chronic HCV after HCV protein exposure appears to parallel, and possibly support, insidiously progressive liver disease." (PMID 18554409, 2008). "In the present study, we have shown that high levels of IL-6, IL-10, and TNF-α could be protective against severe S. mansoni hepatic disease." (PMID 29610679, 2018). "IL-8 levels, along with those for IL-6 and IL-10, are elevated in individuals with alcoholism who have no signs of liver disease." (PMID 26695748, 2015). "Nevertheless, recent studies in patients with other forms of inflammatory liver diseases have not shown benefit of anti-TNF agents or IL-10, and the use of any of these agents would likely increase the risk of infections." (PMID 24386086, 2013).
liver disease (continued). "In the context of liver diseases, cytokines have been assigned fundamental properties reflecting common function, including proinflammatory cytokines (e.g. IL‐1α, IL‐1β, TNF‐α, and IL‐2), immunoregulatory cytokines (e.g. IFN-γ), and anti-inflammatory cytokines (e.g. IL-10 and IL-4)." (PMID 33841403, 2021). "Theoretically, high production of IL-10 could facilitate viral escape by down regulating the protective TH1 response, but at the same time be beneficial to the patient due to its anti-fibrogenic properties that could lead to a slow progression of liver disease." (PMID 22986179, 2012). "IL-6 levels, along with those of IL-8 and IL-10, are increased in patients with ALD who have no clinical signs of liver disease." (PMID 26695748, 2015). "IL-10 expression is moderately to highly increased in ALD and, along with that of IL-6 and IL-8, is also upregulated in alcoholic patients without signs of liver disease." (PMID 26695748, 2015). "Our results, regarding Foxp3, IL-10, and TGF-β1 expression, imply that nTregs, and not iTregs, could contribute by processes unknown as yet to inflammatory liver disease." (PMID 21772667, 2011).
Chagas disease (57 papers, 2009 to 2025). A parasitic infection caused by Trypanosoma cruzi. "Next, we performed a systematic review of the literature of studies on IL-10 polymorphisms and Chagas disease and conducted a meta-analysis to estimate a consensus association estimation." (PMID 35860267, 2022). "Still, in view of the central role of IL-10 in Chagas disease progression we aimed to establish the association between IL-10 polymorphisms and the development of CCC in seropositive T. cruzi patients attending to a hospital in Buenos Aires, Argentina." (PMID 35860267, 2022). "An independent study including 104 CCC patients and 60 noninfected controls suggests that an epistasis between MHC and IL-10 is associated with susceptibility/resistance to Chagas disease." (PMID 25210230, 2014). "Higher levels of IFNγ and TNFα are associated with lower levels of IL-4 and IL-10, in both cardiac and more severe forms of Chagas disease, and high levels of IL-10 or moderate levels of IFNγ are associated with the indeterminate form." (PMID 24216069, 2013). "In human Chagas disease as well the presence of a polymorphic allele of IL-10 gene, which results in lower expression of this cytokine is associated with cardiomiopathy and a severe form of the disease." (PMID 20967289, 2010). "In patients with Chagas disease and preserved EF, the presence of intraventricular conduction disorders appears to be associated with a distinct cytokine profile characterized by elevated IL-10, IL-12p70, IL-2, IL-15, MIP-1α, and IFN-γ." (PMID 41440541, 2025). "Several studies have shown the important role of cytokine-mediated immunoregulation in the maintenance of asymptomatic clinical forms during the progression of Chagas disease, mainly associated with the production of modulatory cytokines IL-10 and pro-inflammatory cytokines TNF-α and IFN-γ." (PMID 30662439, 2018). "Furthermore, in human Chagas disease higher percentages of CD28− T cells have been associated with increased IL-10 production." (PMID 23383358, 2013). "Our data presented in this study provide strong evidence that TcVac3-induced protection from T. cruzi infection and Chagas disease was associated with IL-10-dependent regulatory networks critical for arresting the clinical evolution of disease; to be further delineated in future studies." (PMID 23555672, 2013). "In vitro, treatment with vitamin D revealed a difference in cytokine production by peripheral blood mononuclear cells between patients with chronic cardiac and indeterminate clinical forms of Chagas' disease, with a decrease in IL‐10 in cardiac patients." (PMID 39267468, 2024). "In the chronic phase of Chagas disease, IL-10 participates in delaying the onset of chronic Chagas heart disease (CCD) in infected individuals." (PMID 38543309, 2024). "Studies in various contexts proposed a protective role of high-levels of IL-10 against Chagas disease progression, as these levels can attenuate the inflammatory tissue damage elicited by persistent infection with the protozoa." (PMID 35860267, 2022). "In late stages of Chagas disease, IL-10 participates in delaying the onset of CCC in infected individuals." (PMID 35860267, 2022). "It has been reported that patients with asymptomatic Chagas disease express higher levels of IL-10 than CCC patients." (PMID 33072115, 2020). "IL-10 knockout and WT mice were infected with the K98 clone of T. cruzi, in order to evaluate the role IL-10 on the effects of fenofibrate treatment in an experimental model of Chagas disease." (PMID 33072115, 2020). "In previous reports, we highlighted the relevance of IL-10 in the modulation of the pro-inflammatory response of cardiomyocytes in Chagas disease." (PMID 31214200, 2019). "In human Chagas disease, MMP-2 has been previously associated with regulatory responses in IND patients by correlations with regulatory cytokines, especially IL-10, whereas MMP-9 has been associated with inflammatory response and cardiomyopathy." (PMID 31578449, 2019).